NBPF8 (NBPF member 8)
Synonyms: NBPF8P
Tractability: PROTAC: ubiquitination databases record sites on it.
Gene: Protein-coding gene on chromosome 1 (120,415,035 to 120,469,676, forward strand). Ensembl gene ENSG00000270231.
Subcellular location: Cytoplasm
Subcellular location (Human Protein Atlas): Cytosol; Primary cilium; Cytokinetic bridge; End piece; Golgi apparatus; Microtubules; Mid piece; Principal piece; Vesicles
Gene Ontology:
Cellular component: cytoplasm
Homologues: Paralogues in human: NBPF9 (97% identical), NBPF26 (96% identical), NBPF14 (96% identical), NBPF10 (96% identical), NBPF12 (96% identical), NBPF1 (87% identical), NBPF11 (83% identical), NBPF20 (69% identical), NBPF19 (69% identical), NBPF15 (66% identical), NBPF3 (49% identical), NBPF4 (32% identical), and 1 more.
Diseases named in the same sentence as NBPF8 in open-access papers:
NBPF8 is named in the same sentence as 3 diseases in open-access papers, as found by Europe PMC text mining. Sharing a sentence is not in itself a finding about the gene and the disease. The quoted sentences say what the papers report.
neuroblastoma (1 paper, 2024). Neuroblastoma (NB) is the most common solid, extracranial childhood tumor. "Neuroblastoma Breakpoint Family genes, such as NBPF8, are associated with neuroblastoma, a cancer that arises from nerve cells, often in the sympathetic nervous system." (PMID 39062924, 2024).
NBPF8 also shares sentences with these, for which no sentence is quoted: cancer (1 paper); neurological diseases (1).